CD4 (CD4 molecule)
Diseases named in the same sentence as CD4 in open-access papers (continued):
Sharing a sentence is not in itself a finding about the gene and the disease.
COVID-19 (continued). "Taken together with existing data, our results indicate that adults with HIV receiving suppressive antiretroviral therapy and who have CD4+ T-cell counts in the healthy range, mount broadly comparable “peak” humoral immune responses to two COVID-19 vaccine doses compared to individuals without HIV." (PMID 35228535, 2022). "The number of regulatory T cells (CD3+CD4+CD25+CD127low+), naïve regulatory T cells (CD45RA+CD3+CD4+CD25+CD127low+), as well as induced regulatory T cells (CD45RO+CD3+CD4+CD25+CD127low+) are decreased in the circulation of COVID-19 patients as compared to healthy controls." (PMID 36034704, 2022). "Risk factors related to progression were reported in nonsevere COVID-19 patients, such as lymphocyte count, neutrophil count, CD4+ and CD8+ T cell counts, CRP, D-dimer, interleukin-6, interleukin-8, lactate dehydrogenase, age, dyspnoea on admission, and hypertension." (PMID 35619076, 2022). "However, the authors have not correlated their findings with a severity stratification of COVID-19 patients nor have they performed further sub-analysis of CD4 and CD8 T cells." (PMID 35480624, 2022). "First, at baseline, convalescent COVID-19 donors had significantly higher proportions of central and effector memory CD8+ T cells and central memory CD4+ T cells compared with the MIS-C group, and this may contribute to the weaker antigen-specific T cell activation in MIS-C." (PMID 35044955, 2022). "After focusing on T cell response against nucleocapsid (N) proteins, non-structural protein 7 (NSP7), and NSP13 of convalesced COVID-19 patients, they found CD4+ and CD8+ T cells could recognize multiple regions of N protein." (PMID 36003630, 2022). "We then investigated CD4+, Treg and CD8+ T cells polyfunctionality by analyzing simultaneous production of TNF-α, CD107a, IFN-γ, IL-2, IL-17, granzyme-B and TGF-β by mild, moderate and severe COVID-19 convalescent patients at recovery time-point I and time-point II, as well as by healthy donors." (PMID 35757700, 2022). "Cytofluorimetric analysis of samples derived from COVID-19 patients with severe infection and hospitalized in ICU, with respect to healthy controls and patients with less severe disease manifestations, has shown significantly higher PD-1 expression levels on CD8+ and CD4+ cells from ICU patients." (PMID 36289890, 2022). "The CD4+ T cell activation of the human inflammatory cytokine cascade in response to the major histocompatibility complex binding of pathogen protein fragments (e.g., SARS-CoV-2) contributes to the characteristic hyperinflammation frequently observed in severe COVID-19." (PMID 36615679, 2022). "In conclusion, patients with SARS-CoV-2 induced OTD develop highly functional virus-specific CD4+ and CD8+ T cells during the symptomatic phase of the disease, suggesting that robust and coordinated T-cell responses provide protection against extension of COVID-19 to the lower respiratory tract." (PMID 34858405, 2021). "In particular, the expression of PD-1 and ICOS on CD4+ T cells and that of CD127 and CD40L on CD8+ T cells showed a marked decrease when the majority of blocking antibodies were added, both individually and as a pool, to PBMCs cultured with serum obtained from patients with COVID-19." (PMID 34784300, 2021). "Though evidence of direct involvement of SARS-CoV-2-specific CD4+ T cells in mediating protection is lacking, for effective induction and long-term maintenance of antibody responses against COVID-19, a high-quality helper T cell response might be the key." (PMID 33573221, 2021). "CD19 and CD4 counts were significantly lower in Group D than in Group A. These results suggest worse immune dysfunction in patients with low LDL-C levels, which has been recognized as an important factor in the occurrence and development of COVID-19 since the beginning of the epidemic." (PMID 34124081, 2021).
COVID-19 (continued). "Upon spike protein stimulation or SARS-CoV-2-infection, CD4+ T and CD8+ T cells showed particular features considering the nature of exposition while unexposed, and COVID-19 could represent the first and second virus exposure, respectively, using the in vitro assay." (PMID 34571855, 2021). "Our meta-analysis revealed significantly lower levels of immune cells (CD3+ T, CD4+ T, CD8+ T, B and NK cells), higher levels of cytokines (TNF-α, IL-5, IL-6 and IL-10) and higher levels of chemokines (MCP-1, IP-10 and eotaxin) in severe cases in comparison to mild cases of COVID-19." (PMID 34344353, 2021). "Several studies found that virus-specific CD4+ T cell responses were correlated with the magnitude of the anti-SARS-CoV-2 IgG and IgA against spike protein and nucleocapsid protein, live virus neutralizing antibody titers, and SARS-CoV-2 pseudovirus neutralization titers in COVID-19 patients." (PMID 33573221, 2021). "Moreover, CD4+ T cell responses to non-spike peptides were also increased in OTD-CoV-2pos patients compared with severe COVID-19." (PMID 34858405, 2021). "Hence, determining the cut-off point for T cells, especially CD4+ and CD8+ T cells after the development of COVID-19 symptoms, can be a valuable prognostic indicator and may predict disease progression." (PMID 35126355, 2021). "The aim of the present study was to investigate the laboratory characteristics of the viral load, CD3 + T-cells, CD4 + T-cells and CD8 + T-cells and cytokines in asymptomatic individuals with SARS-CoV-2 infection in comparison with those in symptomatic patients with COVID-19." (PMID 34118952, 2021). "In a study that measured SARS-CoV-2–specific antibodies, CD4+, and CD8+ T cells in participants with a range of COVID-19 disease severities, severe or fatal disease was shown to be associated with minimal or lacking SARS-CoV-2–specific CD4+ and CD8+ T cell responses." (PMID 34591596, 2021). "In addition to CD4+ T cells and neutralizing antibodies, CD8+ T cells contribute to protective immune responses against SARS-CoV-2 in patients with coronavirus disease 2019 (COVID-19), an ongoing pandemic disease." (PMID 34413488, 2021). "Our observations suggest that SARS-CoV-2-specific CD4+ and CD8+ T-cell responses should be considered to better evaluate vaccination and public health strategies, and assessed together with neutralizing antibody titers to predict protection from infection and severe COVID-19." (PMID 35111162, 2021). "Notably, the percentage of Treg-CTLA4 cells increased significantly in most COVID-19 groups over controls, but the proportions of other CD4+ T cell subsets did not change significantly." (PMID 35095917, 2021). "Additionally, increased frequencies of virus-specific cTfh cells (CD4+CXCR5+OX40+CD40L+) were observed in acute and convalescent COVID-19 cases, and the frequencies of both SARS-CoV-2-specific cTfh cells and S-specific CCR6+CXCR3-cTfh17 cells were closely associated with low disease severity." (PMID 34603308, 2021). "The characterization of the T cell subsets in a cohort of 39 COVID-19 with a median age of 64 years (range 35–94) has revealed that a decrease in both the percentage and the absolute number of naïve CD45RA+CCR7+ CD8+ T cells and in the absolute number of naïve CD45RA+CCR7+ CD4+ T cells." (PMID 34595175, 2021). "In patients with non-COVID-19 viral infections, we observed significant increase in proportion for myeloid cells (M1 macrophages, CD14 + monocytes, MAST cells) and significant decrease in proportion for lymphoid cells (CD4+ and CD8+ T cells, gamma-delta T cells, B cells)." (PMID 33437935, 2021). "This suggests that acute COVID-19 does not promote the reactivation of latent M. tuberculosis infection but could enhance the activation of the M. tuberculosis–specific CD4+ T cell response during active TB." (PMID 33945513, 2021).
COVID-19 (continued). "Future studies with an enhanced transfection efficiency of TCRs and corresponding detailed functional verification in vivo may significantly increase the efficacy of SARS-CoV-2-specific CD4+ TCR-T cells and help us to better evaluate this potential therapeutic method for treating COVID-19 patients." (PMID 34805136, 2021). "Reduced CD3+, CD4+, and CD8+ T lymphocyte counts may reflect the severity of COVID-19." (PMID 33436069, 2021). "Global overview revealed enrichment of proliferating CD4+ and CD8+ T cells, and plasma cells in BALF compared to PBMCs, while proliferative and activated T and B cells as well as macrophages were more abundant in patients with severe COVID-19 during progression stage." (PMID 33863870, 2021). "In addition, the obviously higher correlation for MHCII compared to MHCI may indicate that CD4 cells play a more crucial role in fighting against the SARS-CoV-2 infection for the human immune system, in particular for severe COVID-19 patients." (PMID 33807854, 2021). "Hospitalization rates among persons living with diagnosed HIV were higher among those without viral suppression and those with lower CD4 counts, suggesting that more advanced disease may increase COVID-19 severity to the point that hospitalization is required." (PMID 33533933, 2021). "Third, although previous studies reported that functional exhaustion of CD8+ and CD4+ T cells is related to the disease severity of COVID-19, lymphocyte subsets including B cells, CD4+ and CD8+ T cells, and natural killer cells, were not measured in this study." (PMID 33530509, 2021). "Overall, CD4+ T-cells from mild COVID-19 behaved similarly as normal lung or non-COVID-19 BAL." (PMID 33473155, 2021). "Thus, studying antibody, memory B cell, CD4+ T cell, and CD8+ T cell memory to SARS-CoV-2 in an integrated manner is likely important for understanding the durability of protective immunity against COVID-19 generated by primary SARS-CoV-2 infection." (PMID 33408181, 2021). "Based on the RNA-seq of 126 samples from the GEO database, we disclosed that there is a remarkably higher m6A modification level of blood leukocytes in patients with COVID-19 compared to patients without COVID-19, and this difference was related to CD4+ T cells." (PMID 34917088, 2021). "Since CD126 is expressed on both CD4+CD25- conventional T cells as well as on Tregs, tocilizumab could act on both cell types and it was recently shown that tocilizumab treatment also affects the transcriptional signature of Tregs in COVID-19 patients." (PMID 34408743, 2021). "A recent study comparing healthy controls to COVID-19 patients suggest increased secretion of monosialodihexosylganglioside (GM3)-enriched exosomes (increased levels of sphinomyelins (SMs) and reduced DAGs), altering CD4+ T-cell activation, resulting in immunosuppression." (PMID 34571942, 2021). "Previous studies on the lymphocyte subset counts showed close relations between (i) CD4+ and CD8+ T cell counts and (ii) disease severity and clinical outcome, and suggested that the CD4+ and CD8+ T cell counts in patients with COVID-19 could be good biomarkers of COVID-19 activity." (PMID 33350432, 2021). "Furthermore, CD4+ T cells help CD8+ T cells respond to infection, and a high concentration of specific infected cell-destroying CD8+ T cells gives a better prognosis for COVID-19 patients." (PMID 34440721, 2021). "Therefore, a decline in CD4+/CD8+ T cell ratio may serve as a useful metric for reflecting the derangement of immune responses and even mortality in patients with severe COVID-19." (PMID 33937149, 2021). "However, these phenotypes between these two groups of CD4+ T cells of mild and moderate COVID-19 cases exhibit distinct functional signatures, distinct TCR sharing patterns, and may represent two divergent destinations for naive CD4+ T cells." (PMID 35011632, 2021).
COVID-19 (continued). "Furthermore, the analysis revealed a slightly higher, non-significant abundance of CD4+ memory T cells in the LP (cluster 1, p = 0.056) of COVID-19 patients compared to control tissue." (PMID 34420043, 2021). "Interestingly, almost similar magnitude of non-spike specific CD4+ T cells are present in majority of the unexposed and COVID-19 recovery patients." (PMID 33777028, 2021). "However, Tα1 showed no benefit for COVID-19 in our study in the perspective of restoring CD4 and CD8 counts." (PMID 34149679, 2021). "Using T cell receptor (TCR)-dependent activation induced marker (AIM) assay, SARS-CoV-2-reactive CD4+ (CD134+CD137+) and CD8+ (CD69+CD137+) T cells directed toward S, M, N and other ORFs were detected in 100% and 70% of convalescent patients with COVID-19, respectively." (PMID 35004764, 2021). "Furthermore, another study reported that most, if not all, COVID-19 survivors tested were shown to have N-specific CD4 + T-cell responses." (PMID 34290317, 2021). "However, a case study by Suwanwongse and Shabarek (2020) reported a much higher mortality rate (7 out of 9 patients) in HIV-COVID-19 co-infected patients with a significantly lower CD4+ T cell count, than among COVID-19 patients without HIV." (PMID 34295314, 2021). "Therefore, a lower number of CD8+ T cells, along with decreased counts of CD3+, CD4+, CD20+ and NK cells, could significantly contribute to the worst outcomes of COVID-19." (PMID 33669527, 2021). "Interestingly, CD8 T cells, but not CD4 T cells, also showed an increased pyroptotic phenotype in patients with COVID-19." (PMID 34394094, 2021). "Male COVID-19 patients experienced more severe immune dysregulation, with lower CD4+ T cell proportions (P=0.0250), higher CD8+ T cell proportions (P=0.0068), and much lower CD4+/CD8+ ratios (P=0.0131), indicating a possible immune deficiency that is similar to that observed in HIV infections." (PMID 33350432, 2021). "To assess whether exosomes of MILD COVID-19 patients induced T-cell growth by actual T-cell activation, we tested their capability to modulate the expression of middle, CD25, and late, HLA-DR, T-lymphocyte activation markers cocultured in matched CD4+ T cells." (PMID 35111156, 2021). "No increase in effector memory CD4+ T cells was observed in the group of severe COVID-19 patients." (PMID 33692788, 2021). "In addition, there were higher correlations between IL-2 and IL-4, TNF-α and IL-2, TNF-α and IL-4, TNF-α and IFN-γ, and NK cells and T cells in COVID-19 patients, and there was a higher correlation between CD3+CD4+ T cells and CD19 + T cells in cancer patients." (PMID 34712741, 2021). "Multi-omics studies of patients suffering from COVID-19 demonstrated that CD4+ naïve T cells could also differentiate into a group of clonally expanded nonspecific CD4+ cytotoxic phenotype 120." (PMID 34373739, 2021). "The neutrophil to CD4+ T lymphocyte ratio (N4R) and neutrophil to CD3+ T lymphocyte ratio (N3R) showed clinical significance in differentiating severe or critically-severe COVID-19, with area under receiver operating characteristic curves (AUCs) of 0.933 and 0.900, respectively (P < 0.05)." (PMID 33741750, 2021). "This lack of cTfh responses in COVID-19 negative individuals is not surprising, as cTfh compose a minor population of the total CD4 T cells in the blood, and cTfh responses induced by other seasonal coronaviruses, if present, likely exist at very low, undetectable frequencies." (PMID 34270631, 2021). "However, there was a significant negative correlation between anti-SARS-CoV-2 antibody level and CD4/CD8 ratio (Spearman’s correlation coefficient −0.4, p = 0.02), and the relative number of CD8+ T cells (r = 0.41, p = 0.01) in responders to the COVID-19 vaccine." (PMID 34946272, 2021).
COVID-19 (continued). "In our opinion, the lower expression of CD45RO molecules on CD8+ cells may indicate undeveloped or impaired cell memory in COVID-19 patients, as opposed to CD4+ cells, where the expression of this molecule was at the level of the control group." (PMID 33419040, 2021). "Moreover, we compared the expression of α4β7 on SARS-CoV-2-specific CD4+ memory T cells from COVID-19 patients with healthy donors without SARS-CoV-2 infection that also had SARS-CoV-2-specific T cells in their peripheral blood as previously reported." (PMID 33959123, 2021). "Many T cells subsets proliferate during COVID-19, including those that are usually quiescent, such as TCM (central memory) and TEM (effector memory) subsets with 10-fold increases in the percentage of blood CD4+ and CD8+ TEM cells in G1 or S-G2/M cell cycle phases." (PMID 33575657, 2021). "Furthermore, based on SARS-COV-2 peptide stimulations, more than approximately 30-fold higher frequencies of AIM+ CD4+ and CD8+ T cells were detected in convalescent patients with COVID-19 compared to unexposed individuals, confirming the accuracy of the detection system and the AIMs." (PMID 35822004, 2021). "Baseline N4R and N3R could be potential biomarkers for assisting in differentiating COVID-19 severity, and dynamically monitoring peripheral CD3+CD4+ and CD3+CD8+ T cells 6-9 days after baseline could help clinicians to evaluate disease progression in COVID-19 patients." (PMID 33741750, 2021). "Moreover, as specific indexes for the evaluating effect of ART, the impact of a COVID-19 vaccine on CD4+ T cell counts and VL is not conclusive." (PMID 34960204, 2021). "Finally, effector subsets of CD4+ T cells TEM and TEMRA were in higher proportion in severe and critical COVID-19 than mild disease, which may also contribute to the overall decrease of CD4 count." (PMID 34122423, 2021). "Our synthesized results revealed significantly lower levels of immune cells in CD3+ T, CD4+ T, CD8+ T, B and NK cells, higher levels of cytokines (TNF-α, IL-5, IL-6 and IL-10) and higher levels of chemokines (MCP-1, IP-10 and eotaxin) in severe cases compared with mild cases of COVID-19." (PMID 34344353, 2021). "Additionally, we provide a number of early prognostic markers for the onset of severe COVID-19, such as CD14+/CD16+ monocytes ratio, CD4+/CD8+T cell ratio, GZMK+/GZMB+ T cell ratio, etc., although these parameters require further validation in the larger cohorts." (PMID 35095917, 2021). "Additionally, hyperactivation of pre-existing T cells could contribute to short- and long-term disease severity via inflammation and autoimmunity, as increased production of IFN- by CD4+ and CD8+ T cells has been observed in severe COVID-19 patients." (PMID 33853928, 2021). "PBMC of two resolved COVID-19 patients were also stimulated with the SARS-CoV-2 peptide pool but no ex vivo CD4+ T cell response could be detected." (PMID 34529740, 2021). "Besides CD4 TRM cells, whether CD8 TRM cells could contribute to the development of chronic lung sequelae following COVID-19 during aging, as what have demonstrated in influenza pneumonia model, requires further investigation." (PMID 34158111, 2021). "Moreover, in a subset of patients, we investigated whether HIV and/or TB coinfections affected the CD4 response against SARS-CoV-2 and conversely, whether COVID-19 affected the M. tuberculosis–specific CD4 response." (PMID 33945513, 2021). "In the clinic, CD4 + T cell testing is always nonessential for COVID-19 patients." (PMID 33732148, 2020). "Also, severe or critical COVID-19 patients had relatively lower CD3 count (MMD: -380.8 [-515.3, -246.4], I2: 80%), CD4 count (MMD: -204.9 [-302.6, -107.1], I2: 87%) and CD8 count (MMD: -123.6 [-170.6, -76.6] I2: 66%); all differences measured in terms of cells/μl." (PMID 33002041, 2020).